BRAF (B-Raf proto-oncogene, serine/threonine kinase)
Diseases named in the same sentence as BRAF in open-access papers (continued):
Sharing a sentence is not in itself a finding about the gene and the disease.
metastatic colorectal cancer (continued). "The evidence for BRAF mt as a poor prognostic indicator is strongest in metastatic colorectal cancer (mCRC), with worse OS and resistance to EGFR inhibitors." (PMID 34940086, 2021). "In conclusion, high baseline plasma AREG levels predicted worse PFS in patients with RAS/BRAF wild-type metastatic colorectal cancer treated with palliative first-line cetuximab plus FOLFIRI chemotherapy, but not with non-EGFR-directed second-line treatment." (PMID 34893673, 2021). "In this article, we describe the study protocol of MONARCC, a randomised phase II study of panitumumab monotherapy and panitumumab plus 5-FU as first-line therapy for RAS and BRAF wildtype metastatic colorectal cancer." (PMID 34407800, 2021). "Treatment strategies inhibiting BRAF in combination with EGFR have been developed in patients with BRAFV600E mutant metastatic colorectal cancer, but intrinsic and secondary resistance remains a challenge." (PMID 33204026, 2021). "Patient selection for addition of anti-EGFR therapy to chemotherapy for patients with RAS and BRAF wildtype metastatic colorectal cancer can still be optimised." (PMID 34253874, 2021). "The prognostic heterogeneity in patients with BRAF V600E metastatic colorectal cancer (mCRC) remains poorly defined." (PMID 34572480, 2021). "According to other studies on metastatic colorectal cancer (mCRC), TCC patients harboring BRAFV600E mutation showed a significantly worse OS than BRAF wild type." (PMID 32872561, 2020). "We assessed 72 consecutive patients with a diagnosis of metastatic colorectal cancer (mCRC) using IdyllaTM Biocartis, a fully automated platform that evaluates the most frequent mutations of KRAS, NRAS and BRAF genes." (PMID 31597339, 2019). "A total of 779 FFPE samples from patients with metastatic colorectal cancer with valid NGS results were screened and 22 uncommon mutational profiles of KRAS, NRAS and BRAF genes were selected." (PMID 31068650, 2019). "In metastatic colorectal cancer, RAS and BRAF mutations cause resistance to anti‐EGFR therapies, such as cetuximab." (PMID 31350822, 2019). "RAS genotyping is mandatory to predict anti-EGFR monoclonal antibodies (mAbs) therapy resistance and BRAF genotyping is a relevant prognosis marker in patients with metastatic colorectal cancer." (PMID 31068650, 2019). "In patients with metastatic colorectal cancer (mCRC), RAS and BRAF mutations are currently determined by tumor sample analysis." (PMID 31319569, 2019). "The findings of this study point out the importance of different approach for the treatment of BRAF mutant metastatic colorectal cancers based on their microsatelite instability phenotype." (PMID 30427914, 2018). "For e.g., it has been used for detection of mutations in KRAS, BRAF and PIK3CA in metastatic colorectal cancer." (PMID 28095454, 2017). "Treatment and treatment results for unselected metastatic colorectal cancer patients according to BRAF/KRAS gene analyses (446 cases with BRAF analyses, 442 cases with both BRAF and KRAS analyses)." (PMID 26121270, 2015). "The significance of BRAF mutations, microsatelite instability (MSI) status and cyclin D1 expression in patients with metastatic colorectal cancer (mCRC) was evaluated." (PMID 20485284, 2010). "Patients with metastatic colorectal cancer (mCRC) harboring both microsatellite instability-high/deficient mismatch repair (MSI-H/dMMR) and the BRAF V600E mutation represent a distinct clinicomolecular subgroup characterized by aggressive biology and distinct therapeutic challenges." (PMID 42088195, 2026). "RNF43, a WNT signaling pathway negative regulator, can predict the response of BRAF V600E MSS metastatic colorectal cancer against BRAF/EGFR combination therapy, where MSI-H always carries RNF43 wildtype-like, encoding p.G659fs* and presents an intermediate response frequency." (PMID 40860811, 2025).
metastatic colorectal cancer (continued). "The randomized FIRE‐4.5 (AIO KRK0116) trial compared first‐line therapy with FOLFOXIRI (folinic acid, fluorouracil, oxaliplatin, and irinotecan) plus either cetuximab or bevacizumab in B‐Raf proto‐oncogene, serine/threonine kinase (BRAF) V600E‐mutant metastatic colorectal cancer (mCRC) patients." (PMID 39630848, 2025). "A 69-year-old woman with metastatic colorectal cancer (RAS wild-type, microsatellite instability-high, BRAF V600E mutation) receiving encorafenib/binimetinib plus cetuximab developed Grade 2 IR during her first cetuximab infusion (approximately 98 min after initiation)." (PMID 41458789, 2025). "The available evidence regarding anti–epidermal growth factor receptor (EGFR) inhibitor rechallenge in patients with refractory circulating tumor DNA (ctDNA) RAS/BRAF wild-type (wt) metastatic colorectal cancer (mCRC) is derived from small retrospective and prospective studies." (PMID 38592721, 2024). "The phase III BEACON clinical trial made progress in the development of BRAF inhibitors by establishing combined encorafenib/cetuximab as a new standard of care for patients with BRAFV600E metastatic colorectal cancer who progressed to one or two previous lines of chemotherapy." (PMID 39083088, 2024). "Anti-BRAF/EGFR therapy is approved for metastatic colorectal cancer (mCRC) with BRAFV600E mutations, although not all patients respond." (PMID 36779536, 2023). "In patients with metastatic colorectal cancer containing WNT and BRAF mutations, LGK974 is on trial in combination with BRAF inhibitor LGX818 and cetuximab, and its side effects have been evaluated according to the Common Terminology Criteria for Adverse Events (CTCAE) for oncology drugs." (PMID 37047705, 2023). "In metastatic colorectal cancer (mCRC), KRAS, NRAS and BRAF assessment is mandatory for treatment selection and prognostication, as RAS mutations confer resistance to anti-EGFR antibodies and BRAF V600 mutations associate with poor prognosis." (PMID 35347327, 2022). "Knowledge of BRAF status should be standard of care in all metastatic colorectal cancer patients as it is now known to be an adverse prognostic factor, and may play a future role in the management of early stage disease." (PMID 34877621, 2022). "For example, in the poor prognosis of BRAF mutant metastatic colorectal cancer, the dose of some patients could be increased under the guidance of genes to achieve a better curative effect." (PMID 35340156, 2022). "More recently, preliminary results from the phase II NIVACOR trial demonstrated good tolerance and acceptable toxicity of a triple treatment that combined FOLFOXIRI/bevacizumab and nivolumab as first-line treatment in RAS/BRAF mutant metastatic colorectal cancer patients." (PMID 36613445, 2022). "This study aimed to integrate gene alterations associated with predictive and prognostic outcomes in patients with metastatic colorectal cancer (mCRC) with polymerase chain reaction (PCR) and in-house next-generation sequencing (NGS) to detect KRAS, NRAS, and BRAF mutations." (PMID 35723364, 2022). "Other series have shown an ATM mutation prevalence of 15% in metastatic colorectal cancer but no increased prevalence in BRAF mutated cases compared to BRAF wild type metastatic colorectal cancers." (PMID 36079062, 2022). "Outcomes are poorer in metastatic colorectal cancer (mCRC) patients with BRAF V600E mutations than those without it, but the effect of these mutations on treatment response is unclear." (PMID 33446148, 2021). "Given that metastatic colorectal cancer (mCRC) patients underwent genomic profiling for clinically actionable mutations such as KRAS, NRAS, and BRAF analysis routinely with a clinically validated COBAS panel, we rationalized separating this cohort from the remaining patients." (PMID 33014822, 2020).
metastatic colorectal cancer (continued). "Therefore, in the present study, we provide new insight on the role of KRAS and BRAF, not only as prognosis biomarkers, but also as first line standard chemotherapy response biomarkers in metastatic colorectal cancer." (PMID 31952366, 2020). "The PANDA study aims at exploring safety and efficacy of panitumumab in combination with FOLFOX or with 5FU/LV in elderly patients affected by RAS and BRAF wild-type metastatic colorectal cancer, to identify the most promising treatment strategy in this setting." (PMID 29370781, 2018). "Indeed, evidence exists for a high cost–benefit ratio for identifying patients with KRAS and BRAF wild-type metastatic colorectal cancer suitable for treatment with cetuximab and those with HER2-positive breast carcinomas who will respond to trastuzumab." (PMID 26942417, 2016). "The aim was to explore the prognostic significance of IL-6 and markers of systemic inflammatory response (SIR), in particular C-reactive protein (CRP), in metastatic colorectal cancer (mCRC) patients, in the total study population and according to RAS and BRAF mutation status." (PMID 27738330, 2016). "However, BRAF isa strong adverse prognostic factor in metastatic colorectal cancer and alsopost-metastectomy." (PMID 26734788, 2015). "Sixty-two patients with previously untreated KRAS/BRAF wild-type metastatic colorectal cancer were recruited to the study between April 2010 and May 2011." (PMID 26467662, 2015). "Biweekly administration of cetuximab requires only one hospital visit every 2 weeks, and may become a convenient treatment option for patients with KRAS/BRAF wild-type metastatic colorectal cancer." (PMID 26467662, 2015). "The pooled analysis of the CRYSTAL and OPUS trials on metastatic colorectal cancer showed that BRAF mutation was not predictive for treatment with cetuximab in KRAS wild-type patients, but indicated poor prognosis." (PMID 24298448, 2013). "Clinical trial data indicate that the presence of mutated BRAF V600E serves as a negative prognostic indicator for patients diagnosed with metastatic colorectal cancer (mCRC), potentially indicating resistance to EGFR-antibody therapy, particularly in heavily treated individuals." (PMID 39682117, 2024). "Left-sided RAS/BRAF wild-type metastatic colorectal cancer patients with unresectable liver-limited disease at diagnosis may represent a subset of ideal candidates for tailored conversion strategies with the best available benefit–risk ratio, especially those with favorable biological behavior." (PMID 36428606, 2022). "The clinical effectiveness of this treatment for metastatic colorectal cancer with RAS and BRAF wild-type cancer is limited due to primary and acquired resistance." (PMID 41301043, 2025). "The results of a prospective phase 3 clinical trial, BEACON CRC, involving patients with metastatic colorectal cancer led to FDA’s approval of dual therapy with anti-EGFR and a BRAF inhibitor (cetuximab + encorafenib)." (PMID 40977811, 2025). "The BEACON CRC study was conducted to evaluate the efficacy and safety of the combination of the BRAF inhibitor (encorafenib), MEK inhibitor (binimetinib), and EGFR inhibitor (cetuximab) in BRAFV600E–mutant metastatic colorectal cancer patients." (PMID 37686423, 2023). "Based on the limited data from clinical trials available so far, whether in first-line or later-line treatment, the clinical benefit of the BRAF mutation subgroup in the MSI-H/dMMR metastatic colorectal cancer population did not significantly vary from that of non-BRAF mutation population." (PMID 37302081, 2023). "Similar results revealed that mutations in BRAF and SMAD4 were significantly correlated with the overall survival (BRAF: p = 4.47 × 10−6 and SMAD4: p = 0.048) of patients with metastatic colorectal cancer." (PMID 36142267, 2022).
metastatic colorectal cancer (continued). "Aberrant alterations in the HER2 gene are relatively uncommon in metastatic colorectal cancer, with HER2 gene amplification present in approximately 3% of metastatic colorectal cancers, mostly in RAS/BRAF wild-type patients." (PMID 36339570, 2022). "This contrasts with the known adverse prognostic effect of BRAF in metastatic disease and relates to the different prevalence of MSI in mutant BRAF localized versus metastatic colorectal cancers." (PMID 36079062, 2022). "In metastatic colorectal cancer (mCRC), KRAS, NRAS, and BRAF assessment is mandatory for treatment selection and prognostication, as RAS mutations confer resistance to anti-EGFR antibodies and BRAF V600 mutations indicate poor prognosis." (PMID 34771462, 2021). "This all-in-one strategy is particularly relevant for metastatic colorectal cancer cases whose MSI status contributes to tumour prognosis and patient selection for immunotherapy while KRAS, NRAS and BRAF genotyping helps for targeted therapies decision." (PMID 33009475, 2020). "A relevant role for NGS is the prediction of response to anti-EGFR agents in metastatic colorectal cancer (mCRC), where multiple exons from KRAS, NRAS, and BRAF must be sequenced simultaneously." (PMID 31036005, 2019). "Cetuximab is approved for the treatment of metastatic colorectal cancer but its response rate in KRAS, BRAF, NRAS and PIK3CA exon 20 quadruple wild-type tumors accounts for only 41%, leaving a high percentage of non-responders." (PMID 28032592, 2017). "It has been suggested that in order for metastatic colorectal cancer patients to receive a response for treatment with monoclonal antibodies targeting EGFR (panitumumab and cetuximab), the BRAF gene needs to be present as wild-type." (PMID 24298448, 2013). "The aim of this retrospective study was to analyze objective responses, time to progression and overall survival of the patients with metastatic colorectal cancer treated with first-line systemic therapy in respect of KRAS and BRAF status." (PMID 22933967, 2011). "Findings reported in the literature support additional testing of BRAF, PTEN and PIK3CA before anti-EGFR treatment in metastatic colorectal cancer." (PMID 22272141, 2011). "Mutations of the BRAF gene are a negative predictor for anti‐EGFR treatment response and indicators of poor prognosis in metastatic colorectal cancer (mCRC)." (PMID 40302146, 2025). "The paradigm of molecular negative hyperselection, beyond RAS and BRAF, identifies metastatic colorectal cancer (mCRC) patients with the greatest benefit from anti-epidermal growth factor receptor (anti-EGFR) agents." (PMID 41167084, 2025). "Similarly, in metastatic colorectal cancer, biomarker testing for KRAS/NRAS, BRAF V600E, MSI, HER2, and NTRK fusions is essential for selecting systemic therapy and clinical trials." (PMID 41462880, 2025). "In Taiwan, at the time of this study, anti-BRAF agents such as encorafenib were not yet reimbursed or formally approved for first-line use in metastatic colorectal cancer." (PMID 40761242, 2025). "Other metastatic colorectal cancers, such as microsatellite-stable cases and those with alterations in other pathways besides receptor tyrosine kinases/KRAS/BRAF, have fewer targeted options and are treated with cytotoxic chemotherapies or anti-angiogenic therapies." (PMID 39452477, 2024). "Currently, anti-EGFR therapy is mainly used for treating metastatic colorectal cancer patients with wild-type RAS/BRAF, since RAS/BRAF mutant patients do not respond well to anti-EGFR therapy." (PMID 36339570, 2022). "In the clinical practice of metastatic colorectal cancer, tumor molecular characterization is crucial for patient management, as RAS and BRAF status could influence the treatment choice." (PMID 34858176, 2021).
metastatic colorectal cancer (continued). "Within the entity of metastatic colorectal cancer (mCRC), there are substantial differences in tumor biology (i.e., RAS-mutant tumors, BRAF-mutant tumors, tumors with microsatellite-instability or Her2/neu expression) that determine treatment choices and outcome." (PMID 32449003, 2020). "A phase III trial demonstrated that EREG expression can be a predictor for overall survival in oxaliplatin/fluoropyrimidine plus bevacizumab-treated metastatic colorectal cancer patients without RAS and BRAF mutations." (PMID 32587640, 2020). "Clinical trials of immune checkpoint inhibitors have shown remarkable activity in patients with metastatic colorectal cancer with MSI-H, although responses are not dependent on the BRAF mutation status." (PMID 29652830, 2018). "At the pathway level, we detected that the alteration rate (mutation and copy number variation) of the genes involved in MAPK signaling pathways, including FGFR1, FGFR2, FGFR3, FGFR4, BRAF, and MEK, was significantly lower in metastatic colorectal cancer tissue compared to the primary site." (PMID 29038591, 2017). "Impact of BRAF V600E mutations (BRAFV600E), a poor prognostic factor in metastatic colorectal cancer, is lacking in non-CRC gastrointestinal (GI) cancers including pancreatic (PDAC), gastric/gastroesophageal (GEA), hepatocellular carcinoma (HCC), and cholangiocarcinoma (CCA)." (PMID 40163685, 2025). "National and European guidelines recommend a first-line doublet or triplet chemotherapy regimen as induction therapy associated with targeted therapy depending on the KRAS, NRAS and BRAF status for patients with pMMR/MSS non-resectable metastatic colorectal cancer." (PMID 39796718, 2024).